TPX2 (TPX2 microtubule nucleation factor)
Diseases named in the same sentence as TPX2 in open-access papers (continued):
Sharing a sentence is not in itself a finding about the gene and the disease.
breast cancer (continued). "In line with our studies, other groups reported that ASPM, KIF20A, TPX2, AURKA and KIF2C are among the top 11 up-regulated hub key genes identified as potential breast cancer prognostic biomarkers." (PMID 37835564, 2023). "TPX2 mRNA shows the highest correlation with CIN among all detected RNA transcripts across multiple solid tumors, including primary human breast cancers." (PMID 33622270, 2021). "Some of these biomarkers, including E2F8, TPX2 and CACNA1D, have been independently confirmed as tumourigenic or tumour-suppressive in breast cancer, and can thus point towards novel targets for treatment." (PMID 34131308, 2021). "TPX2 has been documented to mediate the cell growth and apoptosis via regulating PI3K/AKT/P21 signaling pathway in breast cancer." (PMID 31417870, 2019). "Therefore, recognizing HMMR as a promising therapeutic target, the study validates the overexpression of HMMR in breast cancer and various pan cancers and its correlation with certain proteins such as AURKA, TPX2, and CDK1 through online databases." (PMID 38576486, 2024). "Additionally, TPX2, targeted by the CDK4/6 inhibitor Ademaciclib, has shown advancements in regulating cell cycle progression primarily in HR-positive breast cancer." (PMID 39596419, 2024). "Moreover, after analyzing breast cancer patient data in the TCGA database using the UCSC Xena web-based tool, again we confirmed a positive correlation between CDC20 and TPX2 expression, as shown in the heat map." (PMID 32285914, 2020). "Unexpectedly, knockdown of Tpx2 in the metastatic mammary carcinoma cell line 6DT1 did not change its proliferation rate in vivo or in vitro, as we had expected from the known role Tpx2 plays in mitosis." (PMID 25368990, 2014). "However, to our knowledge, a large immunohistochemistry (IHC)-based study of TPX2 protein expression has not been performed in primary breast cancers." (PMID 33622270, 2021). "Finally, five hub genes (TPX2, KIF2C, CDCA8, BUB1B, and CCNA2) were identified for further research, which might be used as promising biomarkers to evaluate the distant metastasis of breast cancer." (PMID 31285741, 2019).
hepatocellular carcinoma (32 papers, 2014 to 2026). A malignant tumor that arises from hepatocytes. "In summary, we found that HSG (PTTG1, ANLN, KIF2C, TPX2) was significantly upregulated in hepatocellular carcinoma and that the constructed prognostic risk model can reliably predict the prognosis of hepatocellular carcinoma patients." (PMID 38887516, 2024). "Moreover, TPX2 was recently associated with the hepatoma upregulated gene (HURP) for spindle assembly and stabilisation." (PMID 41402347, 2025). "This study identifies TPX2 lactylation as a critical regulator of hepatocellular carcinoma progression, linking metabolic reprogramming to cell cycle dysregulation." (PMID 40107714, 2025). "Here, we show that TPX2 is lactylated at K249 in hepatocellular carcinoma (HCC) tumour tissues and that this process is regulated by the lactylase CBP and the delactylase HDAC1." (PMID 40107714, 2025). "TPX2 (Xenopus kinesin-like protein 2) has also been found to be upregulated in various tumors, including gastric cancer, colorectal carcinoma, hepatocellular carcinoma, and bladder cancer." (PMID 38459558, 2024). "In the previous studies, TPX2 has been demonstrated as an important biomarker for predicting the evolution of some specific tumors, such as hepatocellular carcinoma and lung adenocarcinoma." (PMID 38643462, 2024). "Previous studies have revealed that TPX2 was closely involved in the immune process of some types of cancer, including lung adenocarcinoma, papillary renal cell carcinoma and hepatocellular carcinoma." (PMID 38643462, 2024). "It has been identified that TPX2 level is correlated with EMT in hepatocellular carcinoma and cholangiocarcinoma." (PMID 37752167, 2023). "TPX2 has been shown to play a role in tumor growth regulation in cervical cancer, hepatocellular carcinoma, and glioma." (PMID 36304254, 2022). "Here, we aimed to investigate the role of TPX2 in the antitumor effect of CD8 + T cells in hepatocellular carcinoma (HCC)." (PMID 35273149, 2022). "Recent studies reported that TPX2 dysregulation was related to the progression of esophageal cancer, hepatocellular carcinoma, and colorectal cancer." (PMID 33892811, 2021). "Knockdown of TPX2 suppresses the invasion and proliferation of hepatocellular carcinoma cells via the deactivation of AKT signaling and suppression of MMP-2 and MMP-9 gene expression." (PMID 33531976, 2021). "Recent studies found that CDK5-mediated phosphorylation of TPX2 (Target protein for Xklp2) at Ser486 stabilizes TPX2 to promote the migration of hepatocellular carcinoma cells." (PMID 35006426, 2021). "Clinical correlation of TPX2 (Targeting protein for Xenopus kinesin-like protein 2) protein expression in HCC (hepatocellular carcinoma) (n = 86)." (PMID 25302620, 2014). "For instance, TPX2 could be a potential target for the treatment of hepatocellular carcinoma (HCC) due to its promotive role in HCC growth." (PMID 35395834, 2022). "Due to its important role in microtubule assembly and mitosis, TPX2 has been found to be over expressed in various human cancers, for instance clear renal cell carcinoma, esophageal carcinoma, hepatocellular carcinoma (HCC), gastric cancer, bladder carcinoma and so on." (PMID 31528121, 2019). "This study investigated the role of TPX2 in hepatocellular carcinoma (HCC) from various aspects using bioinformatic analyses." (PMID 38833082, 2024). "Consistent with previous findings, TPX2 overexpression enhanced CD8+ T cell-mediated antitumor immunity and improved the efficacy of anti-PD-1 therapy in a hepatocellular carcinoma patient-derived xenograft mouse model." (PMID 40362354, 2025). "Furthermore, heightened expression of TPX2 in HCC promotes cell proliferation and invasion through AKT signaling activation and upregulation of MMP2/9, underscoring its potential as a therapeutic target for hepatocellular carcinoma." (PMID 39100078, 2024).
hepatocellular carcinoma (continued). "In the present study, we sought to explore the biological importance of lysine lactylation in hepatocellular carcinoma (HCC) progression by regulating the function of cell cycle regulators and discovered that TPX2 is lactylated at K249 via CBP and HDAC1 in HCC cells." (PMID 40107714, 2025). "In this study, we found that the expression level of TPX2 was obviously higher in hepatocellular carcinoma (HCC) tissues than in matched nontumor tissues." (PMID 25302620, 2014). "The presence of TPX2 was found to trigger accelerated metabolism or clearance of sorafenib, a typical tyrosine kinase inhibitor (TKI), in hepatocellular carcinoma (HCC), leading to resistance of HCC cells to sorafenib." (PMID 38770093, 2024). "Additionally, research has shown that increased TPX2 expression enhanced human CD8+ T-cell-mediated antitumor activity and amplifies therapeutic responsiveness to PD-1 inhibition in hepatocellular carcinoma patient-derived xenograft mouse models, irrespective of anti–PD-1 administration." (PMID 41596347, 2026).
prostate carcinoma (27 papers, 2012 to 2026). A carcinoma that arises from epithelial cells of the prostate gland. "This is consistent with the association of TPX2 with progression in prostate cancer patients." (PMID 34031527, 2021). "In some other cancers, such as cholangiocarcinoma and prostate cancer, TPX2 is considered to be an essential factor for tumor development." (PMID 36927438, 2023). "Mechanically, TPX2 mediates prostate cancer EMT through cyclin-dependent kinase (CDK1)-regulated phosphorylation of ERK/GSK3β/SNAIL pathway." (PMID 36707511, 2023). "The interaction of TPX2 with HR proteins and the observation that TPX2 mRNA levels are upregulated in breast and prostate cancers with BRCA1/2 mutations, suggested a role of TPX2 in the repair of DSBs arising from collapsed replication forks by HR." (PMID 36350633, 2022). "The results of the present study not only expand the current knowledge of TPX2 but also provide a novel theoretical basis for the development of prostate cancer treatments." (PMID 35444697, 2022). "It has previously been verified that the TPX2 gene, located at chromosome 20q11.2, is aberrantly expressed in several types of cancer, including prostate carcinoma." (PMID 35444697, 2022). "For example, the depletion of TPX2 can significantly inhibit prostate cancer and cholangiocarcinoma cell activity and migration, and TPX2 knockdown can inhibit tumor growth considerably in vivo." (PMID 36304254, 2022). "Results of the present study further extended the current knowledge of the TPX2/AR pathway and uncovered the potential of TPX2 in the treatment of prostate cancer." (PMID 35444697, 2022). "According to recent findings, knockout of TPX2 in prostate cancer can induce cell cycle quiescence and apoptosis, reduce the ability of cells to invade, and inhibit cell proliferation." (PMID 36247089, 2022). "In conclusion, the present study revealed the interaction between TPX2 and AR in regulating the proliferation of prostate cancer cells." (PMID 35444697, 2022). "We observed that the knockdown of WDR62 results in loss of TPX2 and AURKA protein suggesting WDR62 regulates the stability of this protein complex in prostate cancer cells." (PMID 34326322, 2021). "Mechanistically, our data demonstrated that WDR62 modulates the activity of AURKA by stabilizing the AURKA/TPX2 protein complex in prostate cancer cells." (PMID 34326322, 2021). "For example, TPX2 is associated with poor survival in gastric cancer, targeting TPX2 can suppress tumor cell growth in prostate cancer, and TPX2 is a potential therapeutic target and a prognostic indicator in clear cell renal cell carcinoma." (PMID 32040444, 2020). "Recently, studies have shown that targeting TPX2 in breast and prostate cancer lowered the rate of chromosome missegregation, and have therefore regarded TPX2 as a candidate biomarker for treatment." (PMID 32266115, 2020). "Several studies have demonstrated that TPX2 is overexpressed in esophageal squamous cell carcinoma, breast, colon and prostate cancer." (PMID 31788359, 2019). "The over-expression of detection for TPX2 can be used as a prognostic indicator and therapeutic target for gastric cancer, prostate cancer, cervical cancer and so on." (PMID 31888692, 2019). "The mRNA expression of AIM1, ERGIC1, TMED3, and TPX2 was studied in six prostate cancer (VCaP, PC-3, MDA-PCa-2b, LNCaP, DU145 and 22Rv1) and three non-malignant prostate epithelial cell lines (RWPE-1, PrEc, EP156T)." (PMID 22761906, 2012). "Taken together, TPX2 is a candidate therapeutic target in majority of prostate cancers, possibly also in advanced and castration-resistant disease." (PMID 22761906, 2012). "AIM1, ERGIC1, and TPX2 were shown to be highly expressed especially in prostate cancer tissues, and high mRNA expression of ERGIC1 and TMED3 associated with AR and ERG oncogene expression." (PMID 22761906, 2012).
prostate carcinoma (continued). "Functional gene ontology annotations for the genes co-expressed (R >0.5 and P<0.001) with AIM1, ERGIC1, TMED3 or TPX2 in clinical prostate cancer samples (n = 66–329)." (PMID 22761906, 2012). "TPX2 has been proposed as a potential drug target in multiple cancer types, and our results reveal TPX2 as a potent candidate drug target also in prostate cancer." (PMID 22761906, 2012). "For instance, high TPX2 expression correlated with poor prognosis in prostate cancer." (PMID 37770979, 2023). "Moreover, TPX2 mRNA levels are increased in BRCA1/2-mutated breast and prostate cancers, and high TPX2 expression levels correlate with the sensitivity of cancer cells to PARP-trapping inhibitors." (PMID 36350633, 2022). "By revealing a novel role of TPX2 in the AR signaling pathway, the present study indicated that TPX2 may be an activator of AR and thus exhibits potential as a novel target for prostate carcinoma treatment." (PMID 35444697, 2022). "Results of previous studies have further indicated that TPX2 may function as a potential target for prostate carcinoma treatment." (PMID 35444697, 2022). "Moreover, TPX2 mRNA levels are increased in BRCA1/2-mutated breast and prostate cancers, and high TPX2 gene expression levels correlate with the sensitivity of cancer cells to olaparib." (PMID 36350633, 2022). "Moreover, the expression of tpx2 or ets-1 is much higher in the metastatic prostate carcinoma than in primary prostate carcinoma." (PMID 34123781, 2021). "Therefore, TPX2 enhanced the activation of the HGF/ETS-1 pathway to enhance the invasion of endocrine-independent prostate carcinoma cells and thus it would be a promising target for prostate carcinoma treatment." (PMID 34123781, 2021). "Next, the correlation between tpx2 with mmp3, mmp9 or ets-1 in prostate carcinoma was examined." (PMID 34123781, 2021). "We hypothesized that WDR62 may regulate the stability or function of the TPX2/AURKA protein complex in prostate cancer cells." (PMID 34326322, 2021). "Furthermore, several genes have never been reported to be associated with MM, but they are oncogenes (e.g., TPX2 is related to gastric cancer and pancreatic cancer; UBE2C is related to prostate cancer and colorectal cancer)." (PMID 31886876, 2019). "Moreover, AIM1, ERGIC1, and TPX2 were shown to be highly expressed specifically in prostate cancer tissues, thereby confirming the results of the bioinformatic surveys." (PMID 22761906, 2012). "In order to illustrate the potential of the selected putative targets in the treatment of hormone-refractory disease, the efficacy of AIM1, ERGIC1, TMED3, and TPX2 silencing in the inhibition of prostate cancer cells cultured in androgen deprived conditions was studied." (PMID 22761906, 2012). "To further confirm that WDR62 is a prostate cancer-specific regulator of the TPX2/AURKA protein complex, we examined WDR62, AURKA, TPX2 genetic dependencies in the DepMap." (PMID 34326322, 2021). "This experiment demonstrated that WDR62 interacts with TPX2 and AURKA likely forming a protein complex in prostate cancer cells." (PMID 34326322, 2021). "Due to the function of AR as an important oncogene in prostate cancer, the effect of AIM1, ERGIC1, TMED3, and TPX2 expression on AR signaling was analyzed." (PMID 22761906, 2012). "Taken together, these results suggest that the expression of the potential novel drug targets AIM1, ERGIC1, TMED3, and TPX2 is promoted by ERG oncogene and androgens in cultured prostate cancer cells." (PMID 22761906, 2012). "The mRNA expression level of tpx2 or ets-1 was much higher in prostate carcinoma than it was in prostate non-tumor tissues." (PMID 34123781, 2021). "Validation of target gene expression patterns in clinical prostate samples confirmed that AIM1, ERGIC1, and TPX2 mRNA levels were significantly elevated in prostate cancer tissues (n = 33), compared to non-malignant control tissue samples (n = 3)." (PMID 22761906, 2012).
prostate carcinoma (continued). "Notably, only a single prostate cancer cell line (VCaP) is represented in the DepMap data and so we do not expect a pan-cancer correlation between TPX2 and WDR62 if the biology of WDR62 is prostate cancer-specific." (PMID 34326322, 2021). "However, TPX2 has not been studied in prostate cancer previously." (PMID 22761906, 2012).
colon carcinoma (19 papers, 2008 to 2024). "TPX2 expression detected by immunohistochemical analysis was associated with depth of tumor, lymph node metastasis, and remote metastasis in colon cancer." (PMID 28069036, 2017). "In colon cancer, TPX2 is strongly associated with the progression of colorectal adenoma to carcinoma." (PMID 28069036, 2017). "In colon cancer, the overexpression of TPX2 was significantly associated with the clinical stage, vessel invasion, and metastasis." (PMID 25914189, 2015). "We have previously demonstrated an aberrant overexpression of the microtubule-associated protein TPX2 in colon cancer using a genome-wide gene expression profiling analysis." (PMID 24341487, 2013). "Here we report further that decreased expression of TPX2 in colon cancer cell line SW620 caused a significant decrease in the level of p-Akt, which is an important signaling pathway for tumor formation." (PMID 24341487, 2013). "As TPX2 expression is linked to poor survival of colon cancer patients, we wanted to further explore the molecular mechanism of its action." (PMID 24341487, 2013). "Our study observed that TPX2 expression was closely associated with tumor stage and lymph node metastasis in colon cancer, suggesting that TPX2 could be important in colon cancer progression." (PMID 24341487, 2013). "This study has shown for the first time that aberrant expression of TPX2 is significantly associated with unfavorable clinicopathologic variables of colon cancer and that overexpression of TPX2 leads to the activation of Akt, a mechanism by which TPX2 promotes proliferation and tumorigenesis." (PMID 24341487, 2013). "Therefore, TPX2 may cause proliferation of colon cancer cells through an activation of the PI3K/Akt signaling pathway, a potential therapeutic target." (PMID 24341487, 2013). "TPX2 has been shown to promote the oncogenesis in the context of several cancers such as gastric cancer, colon cancer and glioblastoma." (PMID 35395834, 2022). "One research identified that miR-548-3p attenuated the progression of colon cancer by targeting protein for Xenopus kinesin-like protein 2 (TPX2)." (PMID 35215154, 2022). "The TPX2 gene is overexpressed in colon cancer, leading to vessel invasion and metastasis of colon cancer cells." (PMID 32503626, 2020). "For instance, Aurora A and TPX2 were found overexpressed in lung cancer cells, different colon cancers and neuroblastoma." (PMID 27148480, 2016). "Elevated expression of TPX2 promotes tumor growth in colon cancer, cervical cancer, pancreatic cancer and esophageal squamous cell carcinoma." (PMID 25302620, 2014). "A Kaplan-Meier analysis of the data also indicated that the expression of TPX2 was significantly correlated with the overall survival (OS) of colon cancer patients (log-rank test, P < 0.001, right)." (PMID 24341487, 2013). "Since TPX2 was correlated with the clinical characteristics of colon cancer, we further investigated the effect of TPX2 on the tumorigenic activity of colon cancer cell lines." (PMID 24341487, 2013). "Strikingly, we found that TPX2 knockdown significantly attenuated the migration and invasion ability of colon cancer cells, which was further shown to be mechanistically associated with AKT-mediated MMP2 activity." (PMID 24341487, 2013). "Together, our results indicated that TPX2 plays a critical role in the tumorigenicity of colon cancer cell lines both in vitro and in vivo." (PMID 24341487, 2013). "To better understand the role of TPX2 in the progression and metastasis of colon cancer cells, we explored the possible roles of metastasis-related molecules downstream of TPX2." (PMID 24341487, 2013). "In summary, we show here for the first time that TPX2 is highly expressed in colon cancer tissues and cell lines." (PMID 24341487, 2013). "TPX2 was overexpressed in 129 of the 203 (60.8%) colon cancer metastatic lesions, with the expression being significantly higher than that in primary cancerous tissue and normal colon mucosa." (PMID 24341487, 2013).